BCL2 (BCL2 apoptosis regulator)
Diseases named in the same sentence as BCL2 in open-access papers (continued):
Sharing a sentence is not in itself a finding about the gene and the disease.
breast carcinoma (continued). "In mouse models of cancer, Bcl-2 expression resulted in delayed tumor development in c-myc driven hepatocellular carcinoma, dimethylbenz(a)anthracene induced mammary tumors, and UV or chemical induced squamous cell carcinomas." (PMID 18382684, 2008). "The present study highlights the importance of bcl-2 in breast cancer in a homogenous patient cohort." (PMID 17430582, 2007). "Bcl-2 also predicts a more favorable outcome in metastatic disease as well as in early breast cancer patients who received heterogeneous adjuvant chemo- and hormonal therapies." (PMID 17430582, 2007). "Bcl-2 is an independent prognostic factor of DFS in curatively resected stage III breast cancer patients and appears to be a useful prognostic factor in combination with c-erbB2 and the number of involved lymph nodes." (PMID 17430582, 2007). "LG2 markers include 190 genes, among which are many oncogenes, (BCL2 (down, breast cancer poor prognosis marker), RAD51 (up), EGFR (up), RUNX3 (up), BCL9 (down) and VAV3 (down) and tumor suppressor gene NME1 (up)." (PMID 17683614, 2007). "Suppression of Bcl-2 expression can overcome cellular resistance to apoptosis induced by the adenovirus type 5 gene E1A in models of ovarian and breast cancer." (PMID 17612393, 2007). "Several studies have demonstrated the independent favourable prognostic impact of Bcl-2 on breast cancer particularly among LN+ patients." (PMID 17092354, 2006). "Relationship between the Bcl-2 protein expression and the clinicopathological factors in breast cancer." (PMID 16839413, 2006). "We generated clones of the human breast cancer line MCF-7 stably expressing known amounts of Bcl-2, or Bcl-XL as determined by quantitative immunoblotting." (PMID 16928273, 2006). "In the present study we examined the effects of downregulation of Bcl-2 and Bcl-xL on the chemosensitivity of breast cancer cells in vitro and in vivo with the aim of using this approach as a specific targeting therapy." (PMID 16280040, 2005). "We examined the relationship between the expression of Bcl-2 and Bcl-xL and chemosensitivity of breast cancer cells, with the aim of developing specific targeted therapy." (PMID 16280040, 2005). "The increase in bcl-2 in the breast cancer line exposed to E2 is consistent with ER-α being responsible for increasing bcl-2." (PMID 15777479, 2005). "Overexpression of Bcl-2 is observed more frequently than overexpression of Bcl-xL (70% versus 40%) in breast cancer tissue, which suggests a more important role for Bcl-2 in conferring drug resistance." (PMID 16280040, 2005). "Bcl-2 and Bcl-xL, to a smaller extent, are major determinants of chemosensitivity in breast cancer cells." (PMID 16280040, 2005). "Four human breast cancer cell lines were examined, and the effects of antisense (AS) Bcl-2 and AS Bcl-xL phosphorothioate oligodeoxynucleotides (ODNs) on chemosensitivity were tested in vitro and in vivo." (PMID 16280040, 2005). "The role of Bcl-2 in determining the chemosensitivity of breast cancer cells was tested in MDA-MB-453 cells expressing low levels of Bcl-2." (PMID 16280040, 2005). "PDGFR-α expression was observed in 39.2% of the breast carcinomas and showed an association with lymph node metastasis (P = 0.0079), HER-2 expression (P = 0.0265) and Bcl2 expression (P = 0.0121)." (PMID 16168125, 2005).
breast carcinoma (continued). "Although AS therapy targeting Bcl-2 and Bcl-xL enhances chemosensitivity in breast cancer cells, the effect of blocking Bcl-2 seems superior to that of Bcl-xL." (PMID 16280040, 2005). "Functional annotation of the meta-signature revealed genes such as Cyclin E and BCL2, which were previously shown to be correlated with survival outcome in breast cancer." (PMID 15598354, 2004). "Previous studies in other models, such as breast cancer cell lines, have demonstrated that androgens can induce a decrease on the expression of bcl-2 and also an atrophy of the mammary ephitelium." (PMID 15588330, 2004). "Tumour samples from patients with locally advanced breast cancer were more specifically stained by anti-Bcl-XL antibody than anti-Bcl-2 antibody, consistent with the result of Western blot analysis." (PMID 12644829, 2003). "Western blot analysis showed that in contrast to Bcl-2, expression of Bcl-XL was markedly increased in breast cancer tissues compared to normal; six out of seven patients showed upregulated expression pattern of Bcl-XL." (PMID 12644829, 2003). "To further support a relationship between bcl-2 and N-BP mediated apoptosis, we now report that forced expression of bcl-2 abrogates ZOL-induced DNA fragmentation which is a consequence of caspase activation in breast cancer cells." (PMID 11986784, 2002). "We previously demonstrated that bcl-2 over-expression increases the malignant behaviour of the MCF7 ADR human breast cancer cell line and enhances nuclear factor-kappa B (NF-k B) transcriptional activity." (PMID 11747334, 2001). "Bcl-2 has been demonstrated to inhibit apoptosis in breast cancer cells in vitro, and the ratio between Bcl-2 and its proapoptotic homologue Bax seems to be an important determinant of cellular sensitivity to induction of apoptosis." (PMID 9514059, 1998). "Expression of the bcl-2 gene was investigated in 218 human breast carcinomas by immunohistochemical analysis." (PMID 9252201, 1997). "Our results suggest a potential important role for bcl-2 expression as a modulator of response to adjuvant therapy in breast cancer." (PMID 7640218, 1995). "Therapy with a BCL-2/BCL-XL inhibitor (navitoclax) in combination with thymidylate synthase inhibitors (raltitrexed or capecitabine) causes marked and prolonged tumor regression in prostate and breast cancer xenograft models." (PMID 40436896, 2025). "In breast cancer cells, hsa-miR-195 induces apoptosis by targeting genes such as Bcl-2 and FASN." (PMID 41210882, 2025). "This combined therapy successfully reduced the lung metastasis rate of breast cancer patients by 84% by increasing the expression of cyt c and simultaneously reducing the expression of Bcl-2, matrix metalloproteinase-9 (MMP-9), and vascular endothelial growth factor(VEGF)." (PMID 41191140, 2025).
breast carcinoma (continued). "Results revealed that DMBA-induced breast cancer caused a significant increase in biochemical parameters such as CEA, CA15.3, CA125, PRL, E2, urea, creatinine, ALT, AST, and ALP and a substantial increase in gene expression of TNF-α and BcL-2." (PMID 40097629, 2025). "A preclinical study evaluating BCL-2 inhibitors and chemotherapy in breast cancer xenograft models demonstrated that BCL-2 targeted agents are more efficacious when used in combination with chemotherapy, which possibly explains the outcome of the VERONICA trial." (PMID 40242242, 2025). "Therefore, the detection of BCL-2 expression is conducive to providing a certain selection reference for the treatment of breast cancer patients with different pathological types." (PMID 40104496, 2025). "The expression of BCL-2 is mainly limited to ER-positive breast cancer cells, suggesting a good prognosis and that ER positivity is a necessary condition for endocrine therapy and may be more sensitive to endocrine therapy." (PMID 40104496, 2025). "Furthermore, the antisense oligonucleotide targeting BCL-2 effectively downregulates BCL-2 expression in breast cancer cells, reducing its inhibitory effect on chemotherapy-induced apoptosis and enhancing therapeutic efficacy." (PMID 40104496, 2025). "Our findings demonstrate that targeting the TRIM25/BRD7/YB1/Bcl-2 signal axis might be a potential therapeutic strategy for the treatment of breast cancer." (PMID 41315221, 2025). "Furthermore, it has been proven that BCL2 expression is a predictor of neoadjuvant chemotherapy in urothelial bladder and breast cancer." (PMID 40361484, 2025). "Quercetagetin induced apoptosis in a small proportion of our cells (approximately 20%), evident in morphological results and supported by the detection of active caspase-3 and decreased BCL2 expression in both human (as previously reported) and murine (JC) breast cancer cells." (PMID 41268058, 2025). "Parallel mechanisms involve mitochondrial regulation of apoptosis—overexpression of anti-apoptotic BCL-2 proteins (e.g., in lymphomas and breast cancers) blocks cytochrome c-mediated apoptosome activation, a vulnerability successfully targeted by the BCL-2 inhibitor venetoclax." (PMID 40510156, 2025). "Finally, in a 4T1 breast cancer study and glioma mouse subcutaneous xenograft study, lipophilic MnP analogs suppressed levels of BCL2, which has been reportedly upregulated in ovarian cancer patients." (PMID 40900760, 2025). "Crude venom exhibits broad-spectrum cytotoxicity across various breast cancer cell lines, primarily through the upregulation of pro-apoptotic markers (e.g., Bax, Caspase-3) and the downregulation of anti-apoptotic markers (e.g., Bcl-2)." (PMID 40364211, 2025). "Accordingly, targeting the TRIM25/BRD7/YB1/Bcl-2 signal axis may be a potential molecular target for early diagnosis of breast cancer and promoting the sensitization of PTX in clinical breast cancer patients." (PMID 41315221, 2025). "Additionally, juglone has been demonstrated to suppress tumor angiogenesis and induce apoptosis in breast cancer cells through the regulation of the BCL-2/Bax signaling pathway." (PMID 39948289, 2025). "Experimental evidence indicates that BCL-2 inhibition with Venetoclax and Hedgehog (Hh) pathway suppression in breast cancer can induce Treg conversion toward a Th17-like phenotype, reducing their immunosuppressive capacity, promoting effector cell infiltration, and amplifying antitumor responses." (PMID 41394821, 2025). "Looking ahead, combining dual-targeted therapies involving CDK4/6 and the BCL-2 pathway may provide an effective strategy for treating HR+ breast cancer." (PMID 40104496, 2025).
breast carcinoma (continued). "Moreover, there was growing evidence supporting the regulatory role of phytochemicals in modulating the Bax/Bcl-2/caspase-3 signaling pathway in breast cancer." (PMID 40650258, 2025). "Additionally, the m6A reader YTHDF1 positively regulates the translation of Bcl-2 protein in breast cancer cells by recognizing and binding to m6A sites." (PMID 39972266, 2025). "Thus, targeting Bcl-2 anti-apoptotic members has emerged as one of the most promising approaches in breast cancer therapy." (PMID 40949156, 2025). "miR-195 targets de novo lipogenesis genes, a hallmark in cancer cells especially in aggressive tumors, and that are related to the production of cell membranes for rapid cell proliferation through action on overexpressed target genes in breast cancer such as BCL-2, FASN, ACACA, and HMGCR." (PMID 38813102, 2024). "Besides breast cancer combination regiments, we are also able to use DcNP technology to formulate two leukemia regiments: venetoclax (Bcl-2 target) and zanubrutinib (BTK target) as a synchronized and long-acting drug-combination for the treatment of leukemia." (PMID 39199565, 2024). "As an oncogene, METTL3 may introduce the methyl group into the mRNA of target genes such as MYC and BCL2, promoting its translation that leads to cell differentiation and proliferation and affects apoptosis in acute myeloid leukemia and breast cancer." (PMID 38966069, 2024). "BCL2 is widely acknowledged as a critical clinical prognostic marker in breast cancer." (PMID 38785978, 2024). "A positive ER status was observed in all breast cancer patients with BCL2 gene expression." (PMID 39202273, 2024). "The BCL2 gene, while previously known for its extensive study in breast cancer, especially ER-positive breast cancer, and its subtype-specific prognostic role, exhibited a marked change in its staining pattern within HER2-positive breast cancer according to the IHC result." (PMID 39682150, 2024). "Finally, we also show that TMCO1 silencing can promote apoptosis to navitoclax and S63845, inhibitors of the BCL-2 anti-apoptotic protein family in basal breast cancer cell lines." (PMID 39353922, 2024). "The administration of CB therapy triggers early death in breast cancer cells, as evidenced by upregulation of cleaved caspase 3, downregulation of Bcl2 and survivin, an elevation of reactive oxygen species (ROS), and disruption of mitochondrial membrane potential." (PMID 38563878, 2024). "In addition, our findings showed that, in comparison to normal control and other treatment groups, the anti-apoptotic gene Bcl-2 expression was significantly higher (p < 0.01) in rats bearing breast cancer." (PMID 38233443, 2024). "Hence, Bcl-2 expression can serve as an indicator for determining the sensitivity of breast cancer to chemotherapy." (PMID 38001342, 2024). "The therapeutic significance of PRKACA expression in cancer had previously been suggested by a breast cancer study, which showed that PRKACA mediates resistance to anti-HER2 therapy in breast cancer cell lines via inactivation of BAD and Bcl2-associated death promoter." (PMID 39458904, 2024). "In addition, RHAMM interacts with CD44 to activate ERK1/2 in breast cancer cell lines, and CD44 is reported to upregulate MDR1 microRNA-21 (miR-21), resulting in MDR1 (multi drug resistance protein 1) or anti-apoptotic protein Bcl2 in breast cancer cells." (PMID 39518040, 2024). "The bcl-2 oncogene is overexpressed in 50% to 70% of all human cancers, as well as breast cancers." (PMID 39319107, 2024). "The treatment of breast cancer cell lines, MCF-7 and MDA-MB-231, with andrographolide, demonstrates an inhibition of Bcl-2 and an increase in the expression and protein levels of Bax, further demonstrating the apoptotic effect of andrographolide on these breast cancer cell lines." (PMID 39301125, 2024).
breast carcinoma (continued). "Similarly, 13-O-acetylsolstitialin A, derived from Centaurea cyanus activated the decrease of MMP and increased BAX/Bcl-2 ratio to induce apoptosis in breast cancer." (PMID 38966207, 2024). "Furthermore, the role of Bcl-2 and Mcl-1 is not limited to apoptosis; they play a vital role in cell cycle progression, especially in breast cancer." (PMID 39407625, 2024). "Previous studies showed that nettle plants exhibit pro-apoptotic activity on breast cancer cells as revealed by the increase in the Bax:Bcl2 ratio while increasing the mitochondrial membrane permeability and promoting the release of cytochrome c into the cytosol of PC3 prostate cancer cells." (PMID 39456397, 2024). "The inhibition of ZKSCAN3 using shRNA in MCF-7 and MDA-MB-231 cells diminishes cell viability, migration, and invasion, highlighting that ZKSCAN3-shRNA significantly decreases the expression of MMP-2, MMP-9, CCND1, and Bcl-2 while augmenting the expression of Bax in breast cancer cells." (PMID 39519085, 2024). "Similarly, noscapine increased Bax protein expression and decreased Bcl-2 expression in the MDA-MB-231 breast cancer cell line; there was also an increase in the Bax/Bcl-2 ratio in all three types of cells." (PMID 38542508, 2024). "Additionally, it altered BCL2/Bax signal transduction and triggered apoptosis in breast cancer cells exposed to γ radiation." (PMID 38993643, 2024). "Therefore, our study will primarily focus on both the Invitro and Insilco parameters for targeting the highly dysregulated Bcl2 in breast cancer." (PMID 38223131, 2024). "Ilamycin E was proven to activate the CHOP/Bcl-2 axis and promote apoptosis of breast cancer cells." (PMID 38360722, 2024). "BCL2 is highly expressed in approximately 75% of primary breast cancers." (PMID 38928195, 2024). "We next measured the expression of apoptosis-associated proteins BAX, Bcl-2 and PUMA in mammary tumor tissue from each group in order to determine the impact of single and combined BSp and/or Ash administration on apoptosis induction in mammary tumor." (PMID 38802425, 2024). "MiR-185-5p, for example, can regulate cell apoptosis in breast cancer by targeting BCL2, and could be used as a therapeutic option in the treatment of breast cancer." (PMID 37525284, 2023). "Moreover, we identified miR-134-3p, whose expression was described to be down-regulated in breast cancer, while overexpression of this miRNA was reported to reduce breast cancer cell proliferation through targeting of apoptosis-inhibiting genes like BCL2." (PMID 35779228, 2023). "However, a previous study showed that overexpression of Bcl-2 increased sensitivity to both paclitaxel and vinorelbine in lung and breast cancer cells and significantly potentiated the in vivo efficacy of paclitaxel." (PMID 37569629, 2023). "We observed a decrease in Bcl-2 expression in breast cancer compared to normal breast tissue." (PMID 37370761, 2023). "For example, it has been proven that quercetin suppressed the activation of PI3K and AKT, which increased the ratio of BAX/Bcl-2 to induce apoptosis of breast cancer cells, as well as significantly inhibiting the growth and metastasis of CD44+/CD24 breast cancer stem cells in vivo." (PMID 36900408, 2023).